MMP7 (matrix metallopeptidase 7)
Diseases named in the same sentence as MMP7 in open-access papers (continued):
Sharing a sentence is not in itself a finding about the gene and the disease.
cholangiocarcinoma (13 papers, 2009 to 2024). A carcinoma that arises from the intrahepatic biliary tree (intrahepatic cholangiocarcinoma) or from the junction, or adjacent to the junction, of the right and left hepatic ducts (hilar cholangiocarcinoma). "Serum MMP-7 appears to be a valuable diagnostic marker in the discrimination of cholangiocarcinoma from benign biliary tract disease." (PMID 19405942, 2009). "The authors observed enhanced MMP-7 concentrations in the serum of patients with cholangiocarcinoma." (PMID 33916127, 2021). "Surprisingly, low doses of CX-4945 increased the invasive properties of cholangiocarcinoma cells due to an upregulation of matrix metallopeptidase 7 (MMP-7), while the knockdown of CK2 inhibited cell invasion." (PMID 30142881, 2018). "Recently, several reports have shown that MMP-7 is up-regulated in both cholangiocarcinoma cells and tissues." (PMID 27608843, 2016). "Previous studies have demonstrated that cholangiocarcinoma specimens frequently express MMP-7 (75.8–100%)." (PMID 19405942, 2009). "Previous studies have demonstrated that the expression of MMP-9 and MMP-7 can be detected in cholangiocarcinoma specimens." (PMID 19405942, 2009). "Previous studies determined that expression of MMP-7 in cholangiocarcinoma is an unfavorable postoperative prognostic factor for cholangiocarcinoma patients." (PMID 19405942, 2009). "Our study shows that the serum MMP-7 level is significantly higher in patients with cholangiocarcinoma than with benign biliary tract diseases." (PMID 19405942, 2009). "As far as we are aware, no other published investigation is available that uses the serum MMP-7 level to diagnose cholangiocarcinoma." (PMID 19405942, 2009). "Further prospective studies for serum MMP-7 measurement should be carried out to further investigate the potential of this molecule as a biomarker of cholangiocarcinoma." (PMID 19405942, 2009). "In contrast, the serum MMP-7 values in the cholangiocarcinoma patients (mean ± SD; 8.9 ± 3.43 ng/ml) were significantly higher than those in the control patients (mean ± SD; 5.9 ± 3.03 ng/ml), (Student's t-test; p < 0.001, 95% CI 1.34–4.47)." (PMID 19405942, 2009). "Further studies that include many cases of resectable cholangiocarcinoma need to be completed before the serum MMP-7 level can be used as a prognostic factor for cholangiocarcinoma." (PMID 19405942, 2009). "To date, there is no published study on the detection of serum levels of MMP-9 and MMP-7 in cholangiocarcinoma patients." (PMID 19405942, 2009). "Interestingly, AUC analysis showed that MMP-7 was more accurate than CA 19-9 in diagnosing cholangiocarcinoma." (PMID 33916127, 2021). "Therefore, in our study, the accuracy of serum MMP-9 and MMP-7 levels were investigated in an effort to find a reliable serum marker that can discriminate the benign biliary tract diseases from cholangiocarcinoma." (PMID 19405942, 2009). "The elevation of serum MMP-7 levels could be a very useful tool for the detection of cholangiocarcinoma, especially in those patients with obstructive jaundice." (PMID 19405942, 2009). "To determine whether the values of serum MMP-9 and MMP-7 were predictive of cholangiocarcinoma independently of other tumor markers, we carried out a logistic regression analysis." (PMID 19405942, 2009). "In addition, we also found that the accuracy of the serum MMP-7 level for the diagnosis of cholangiocarcinoma is better than the serum level of MMP-9, CEA and CA19-9, as observed by calculating the AUC of the ROC curve." (PMID 19405942, 2009). "Our study demonstrated that use of serum MMP-7 could identify cholangiocarcinoma patients from benign biliary tract disease patients." (PMID 19405942, 2009). "An receiver operating characteristic (ROC) curve analysis revealed that the detection of the serum MMP-7 level is reasonably accurate in differentiating cholangiocarcinoma from benign biliary tract disease patients (area under curve = 0.73; 95% CI = 0.614–0.848)." (PMID 19405942, 2009).
cholangiocarcinoma (continued). "However, further larger prospective studies that evaluated the benefit of serum MMP-7 in helping the physician to take decisions on diagnosis cholangiocarcinoma are necessary before the implementation of using serum MMP-7 as a marker for cholangiocarcinoma." (PMID 19405942, 2009). "In addition, WTAP overexpression in cholangiocarcinoma induced the expression of metastasis-related genes such as cathepsin H, matrix metallopeptidase 7 (MMP7), matrix metallopeptidase 28 (MMP28), and mucin 1 (Muc1); however, the specific regulatory mechanisms have not been investigated." (PMID 36139062, 2022). "Therefore, detection of MMP-9 and MMP-7 in the blood circulation may be useful for the clinical diagnosis of cholangiocarcinoma." (PMID 19405942, 2009). "Other tumor markers that have been studied for diagnosis of cholangiocarcinoma include transthyretin (TTR), interleukin-6 (IL-6), mucin-5AC (MUC5AC) and matrix metalloproteinase-7 (MMP-7)." (PMID 25355800, 2015). "Among the serum levels of CEA, CA19-9, MMP-7 and MMP-9, only the serum MMP-7 level was significantly higher in the patients with cholangiocarcinoma (8.9 ± 3.43 ng/ml) compared to benign biliary tract disease patients (5.9 ± 3.03 ng/ml) (p < 0.001)." (PMID 19405942, 2009). "Previous studies have demonstrated that matrix metalloproteinase (MMP)-7 and MMP-9 are frequently expressed in cholangiocarcinoma specimens." (PMID 19405942, 2009). "We measured the level of CEA, CA19-9, MMP-7 and MMP-9 in the serum of 44 cholangiocarcinoma and 36 benign biliary tract diseases patients." (PMID 19405942, 2009). "Additionally, in bioinformatics analyses of gene expression data sets in intrahepatic (iCCA) and extrahepatic (eCCA) cholangiocarcinomas, DKK1 was identified alongside MMP7 as a distinguishing marker between these cancer types." (PMID 39236081, 2024). "In cholangiocarcinoma (CCA) cells, magnolol significantly inhibits cell growth, migration, and invasion, accompanied by decreased expression of Ki67, proliferating cell nuclear antigen (PCNA), matrix metalloproteinases 2 (MMP-2), MMP-7, and MMP-9." (PMID 31240205, 2019). "Due to the significant difference of the serum AST, ALP, total bilirubin and direct bilirubin between the control and cholangiocarcinoma patients, we investigated the correlation between the values of these blood chemistries and the values for CEA, CA19-9, MMP-9 and MMP-7." (PMID 19405942, 2009). "This study was designed to determine whether the serum levels of MMP-7 and MMP-9 can discriminate cholangiocarcinoma patients from benign biliary tract disease patients in comparison to carcinoembryonic antigen (CEA) and carbohydrate antigen 19-9 (CA19-9)." (PMID 19405942, 2009). "The objective of this study was to determine the accuracy of detecting serum levels of MMP-9 and MMP-7 for the diagnosis of cholangiocarcinoma in patients without primary sclerosing cholangitis." (PMID 19405942, 2009).
chronic kidney disease (13 papers, 2012 to 2025). Impairment of the renal function secondary to chronic kidney damage persisting for three or more months. "Clinically, MMP-7 has been associated with cardiovascular diseases in various contexts, including carotid atherosclerosis, chronic kidney disease, and type 2 diabetes with hypercholesterolemia." (PMID 39200884, 2024). "Matrix metalloproteinase-7 (MMP7) is markedly expressed in patients with chronic kidney disease; its expression in dialysate and role in patients undergoing peritoneal dialysis (PD) have not been well established." (PMID 37181812, 2023). "MMP7 is significantly increased and acts as a noninvasive biomarker of prefibrotic signaling in patients with chronic kidney disease." (PMID 37181812, 2023). "MMP-7 is barely expressed in healthy adult kidneys, but both animal models and clinical findings suggest that its expression is upregulated in chronic kidney disease." (PMID 36534664, 2022). "Many scientists have hypothesized that MMP-7-induced alterations to the extracellular matrix contribute to the onset of chronic kidney disease (CKD)." (PMID 40027896, 2025). "Additionally, MMP7 mRNA expression is markedly upregulated in kidney tissues of chronic kidney disease patients." (PMID 37266145, 2023). "MMP‐7 is reactivated in a host of disease states, including cancer and chronic kidney disease." (PMID 34117704, 2021). "MMP-7 is barely expressed in normal adult kidney but upregulated in acute kidney injury (AKI) and chronic kidney disease (CKD)." (PMID 32630493, 2020). "Our study describes for the first time the disturbed Hsp27 concentrations, and the potential role of sFas/sFasL, MMP-7 and TIMP-1 in their regulation, in children with chronic kidney disease treated conservatively and on chronic dialysis." (PMID 22528051, 2012).
colitis (13 papers, 2013 to 2025). Inflammation of the colon. "MMP7 expression in inflammatory and endothelial cells suggests that it has a role in both colitis-associated neoangiogenesis and inflammatory changes." (PMID 23724058, 2013). "In a mouse model of colitis with MMP-7 knockout, recruitment of neutrophils is significantly delayed." (PMID 40153427, 2025). "Of note, Mmp7 has recently been shown to degrade the tight junction protein claudin-7 in the colon of a mouse model of colitis, leading to increased bacterial translocation." (PMID 37039638, 2023). "PD down-regulates the expression level of MMP-7, accompanied by a decrease in the infiltration of innate immune cells, which suppresses colonic inflammation and consequently, ameliorates colitis." (PMID 35933374, 2022). "We first verified MMP-7 elevation in patients with UC, as well as in multiple murine models of colitis representing various disease states of IBD." (PMID 36275703, 2022). "In vivo studies with MMP7-null mice provided evidence that MMP-7 mediates epithelial barrier dysfunction, and that MMP-7 deficiency ameliorates colitis." (PMID 36275703, 2022). "To corroborate these clinical findings, we assessed Mmp7 mRNA expression in multiple widely used murine models of colitis with different disease states using RT-qPCR." (PMID 36275703, 2022). "In the present study, we elucidate the mechanism of action of PD in a DSS-induced colitis mouse model and identify MMP-7 as an important regulator of leukocyte recruitment in murine colitis." (PMID 35933374, 2022). "Our results show that MMP-7 is highly expressed in the colon of patients with UC and murine models of colitis." (PMID 36275703, 2022). "The colonic infiltration of MMP-7+ Ly6G+ neutrophils is significantly decreased in the PD-administered DSS-induced colitis mouse model, revealing a positive correlation between the neutrophil infiltration and the expression of MMP-7." (PMID 35933374, 2022). "The expression of MMP-7 was assessed in colonic biopsies of patients with ulcerative colitis (UC), in rodents with experimental colitis, and in cell-based assays with cytokines." (PMID 36275703, 2022). "MMP-7 antibody significantly ameliorated colonic inflammation and Claudin-7 reduction in 2 different rodent models of colitis." (PMID 36275703, 2022). "Several proteins, such as β-catenin and MMP7, have been associated in human studies with tumor formation and its progression, and it has been suggested that elevated levels of Wnt/β-catenin signaling activity could be critical for the colitis-to-cancer transition." (PMID 28301579, 2017). "The coumarin, auraptene, is found in several citrus fruits and has been shown to inhibit MMP-7 activity following DSS induced colitis." (PMID 25948887, 2015). "2′,4′,6′-Tris (methoxymethoxy) chalcone (TMMC) protected against TNBS induced colitis and was able to inhibit MMP-7 upregulation induced by TNF-α in HT-29 cells." (PMID 25948887, 2015). "Finally, the expression of the revealed hub genes related to acute colitis (C3, Tyrobp, Mmp3, Mmp9, Timp1) and CAC (Timp1, Adam8, Mmp7, Mmp13) was validated by qRT-PCR in the colon tissue of mice with acute colitis and colitis-driven adenomas." (PMID 36901742, 2023). "MMP-7 was highly expressed in patients with UC and in rodents with experimental colitis." (PMID 36275703, 2022). "This was further supported by our findings in WT and Mmp7-/- mice subjected to DSS colitis." (PMID 36275703, 2022). "However, in the DSS-induced colitis mouse model, the recruitment of neutrophils is markedly delayed in MMP-7−/− mice." (PMID 35933374, 2022). "In addition to neutrophil infiltration, the MMP-7+ F4/80+ macrophage infiltration is significantly decreased in colonic tissues in the PD-administered DSS-induced colitis mouse model." (PMID 35933374, 2022). "Moreover, MMP-7 antibody treatment markedly mitigated against colitis in rodents treated with DSS or TNBS, demonstrating its therapeutic potential." (PMID 36275703, 2022).
colitis (continued). "However, in the DSS-induced colitis mouse model, the localization of MMP-7 expression was shifted to the edge of the ulcers and the infiltrating immune cells." (PMID 35933374, 2022). "In a DSS induced model of chronic colitis described previously, wild type animals recovered more quickly and completely from the colitis than MMP-7−/− animals which may be due to decreased neutrophil infiltration to the mucosa." (PMID 25948887, 2015). "We next induced colitis with 3% DSS in 6-week-old C57BL/6 wild type mice and age-matched Mmp7-/- mice." (PMID 36275703, 2022). "A recent transcriptomic report comparing gene expression profiles between DSS-induced colitis mice and UC patients has revealed that MMP-7 is differentially expressed in both DSS-induced colitis and UC, suggesting the importance of MMP-7 in UC." (PMID 35933374, 2022). "Most MMPs, such as MMP-2, MMP-3, MMP-7, MMP-9, MMP-10, MMP-12, and MMP-13 are increased in colitis and CAC." (PMID 36776395, 2022). "Together, these data reveal that PD suppresses the infiltration of macrophages by inhibiting MMP-7 and the production of TNF-α in the DSS-induced colitis mouse model." (PMID 35933374, 2022). "The result showed that MMP-7 is expressed by CD45+ infiltrating immune cells, including Ly6G+ neutrophils and F4/80+ macrophages, in DSS-induced colitis mice." (PMID 35933374, 2022). "The MPO activity was elevated >5-fold by DSS in C57BL/6 WT mouse colon, but by only 2-fold in Mmp7-/- mouse colon, compared to the respective controls, suggesting that MMP-7 knockout protected against colitis." (PMID 36275703, 2022). "Despite the extensive studies of MMPs as candidate marker genes of colitis and CAC, to the best of our knowledge, the complex evaluation of the expression of Mmp3, Mmp7, Mmp9, and Mmp13 in acutely inflamed, adenomatous, and adjacent colon tissues has not yet been reported." (PMID 36901742, 2023). "In a transcriptomics study, the genes encoding MMP-7 and MMP-13 were overexpressed in CAC but not in colitis." (PMID 38288108, 2023). "While Claudin-7 mRNA levels were not altered in both WT and Mmp7-/- mice, loss of Claudin-7 protein was confirmed in WT mice treated with DSS, but not in Mmp7-/- mice with DSS colitis, confirming posttranscriptional degradation of Claudin-7 by MMP-7." (PMID 36275703, 2022). "Additional studies using in vivo models of colitis and CAC found that the expression signature of colitis (i.e., Mmp3 and Mmp9) versus that of CAC (i.e., Mmp7 and Mmp13) could predict the development of CAC in mice with dextran sulfate sodium (DSS)-induced colitis." (PMID 38288108, 2023). "Since MMP-7 was detected both in colonic epithelial cells and inflammatory cells in colonic sections from UC patients, we were interested in which cell type could express MMP-7 in the DSS-induced colitis mouse model." (PMID 35933374, 2022). "Comparing the transcriptomes of mice with DSS-induced colitis (without SpNS) and control mice indicated an expected induction of genes encoding pro-inflammatory cytokines, such as TNF-α, and genes involved in wound healing and remodeling, such as Matrix Metalloproteinase (MMP)-7." (PMID 35715845, 2022).
non-small cell lung carcinoma (13 papers, 2012 to 2025). A group of at least three distinct histological types of lung cancer, including non-small cell squamous cell carcinoma, adenocarcinoma, and large cell carcinoma. "In a recent study, CTHRC1 serves as a prometastatic gene of non-small cell lung cancer, and the invasion and metastasis ability mediated by it were MMP7- and MMP9-dependent." (PMID 33564303, 2021). "It has been reported that AEG-1 promotes non-small cell lung cancer (NSCLC) cell invasiveness by the MAPK-dependent activation of matrix metallopeptidase 7 (MMP7)." (PMID 33918653, 2021). "Increased expression of MMP9 was associated with poorer outcomes in nasopharyngeal carcinoma patients and together with increased expression of CTHCR1 and MMP7, higher expression of MMP9 was associated with a lower survival rate after surgery in non-small cell lung cancer patients." (PMID 33717164, 2021). "In addition, CTHRC1 induces non-small cell lung cancer invasion by upregulating MMP-7/MMP-9." (PMID 34968391, 2021). "However, the invasion and migration of human non-small cell lung cancer NCI-H460 cells are suppressed by α-tomatine through inactivating the focal adhesion kinase/PI3K/Akt signaling pathway, which reduces the binding activity of nuclear factor (NF)-κB and downregulates the MMP-7 expression." (PMID 31941156, 2020).
oral cancer (13 papers, 2011 to 2024). "GAD1 knockdown inhibits the cellular invasiveness and migratory abilities of human oral cancer cells by regulating β-catenin translocation and MMP7 activation." (PMID 38553479, 2024). "MMP-7 is mainly expressed in the invasive portion of oral cancer, whereas MMP-8 and MMP-9 are mainly detected in peritumoral inflammatory cells." (PMID 36275775, 2022). "NDV infection in oral cancer cells results in migration inhibition by a reduction in levels of MMP-7." (PMID 31350432, 2019). "In contrast, overexpression of SIRT1 in oral cancer cells caused a significant reduction of MMP7 activity, while TGF-β stimulation was slightly reversed the increase in MMP7 activity (p <0.05)." (PMID 25424420, 2014). "In summary, our data show that SIRT1 inhibited the EMT process in oral cancer by deacetylating Smad4 and repressing expression of MMP7." (PMID 25424420, 2014). "These experiments showed that Smad4 regulates and is required for MMP7 expression, secretion, and activity in oral cancer." (PMID 25424420, 2014). "In contrast, SIRT1 silencing in oral cancer cells resulted in a significant induction of MMP7 secretion." (PMID 25424420, 2014). "In these oral carcinoma cell lines, IL-8 was shown to have positive influence on migration and invasion via up-regulation of MMP-7." (PMID 21958730, 2011). "Our findings suggest the SIRT1/Smad4/MMP7 pathway as a target for oral cancer driven by EMT." (PMID 25424420, 2014). "Kimura et al6 demonstrated that GAD1 promotes the cancer cell invasion and metastasis of oral cancer by inducing the nuclear translocation of β‐catenin and secretion of MMP7,15, 16, 17, 18, 19, 20 although the regulatory mechanisms of GAD1 in β‐catenin translocation remain unclear." (PMID 31207151, 2019). "The expression levels of MMP7, MMP13 and MMP10 were validated to be significantly upregulated in oral cancer compared with normal samples according to the data mining of published profiles in Oncomine." (PMID 31996191, 2020). "Similarly, expression of genes involved in EMT as well as metastasis such as VIM, TWIST and MMP7 were reduced upon silencing of YY1 in qRT-PCR experiment, indicating a regulatory role of YY1 in metastasis and invasion of oral cancer." (PMID 31217904, 2019). "Thus, SIRT1 participates in regulation of MMP7 activity and expression by deacetylating K37 of Smad4, and repressing the effect of TGF-β signaling in oral cancer." (PMID 25424420, 2014). "MMP7 expression has been significantly correlated with oral cancer metastasis and EMT, which suggests that the SIRT1 overexpression might affect MMP7 expression in OSCCs." (PMID 25424420, 2014).